FTH1 (ferritin heavy chain 1)
Diseases named in the same sentence as FTH1 in open-access papers (continued):
Sharing a sentence is not in itself a finding about the gene and the disease.
glioma (continued). "In glioma, the lncRNA TUG1 undermines the antiglioma efficacy of dihydroartemisinin (DHA) by suppressing ferroptosis through the MAZ/FTH1 axis." (PMID 39267831, 2024). "Pre-treatment with ROS scavengers N-acetylcysteine (NAC) and Trolox (6-hydroxy-2,5,7,8-tetramethylchromane-2-carboxylic acid) attenuated RSL3-induced Par-4 induction, LC3-II conversion, and p62/SQSTM1, FTH1, and NCOA4 degradation in glioma cells." (PMID 38886572, 2024). "Modulating TUG1 expression or inhibiting FTH1 can augment the antiglioma effects of DHA, presenting a promising strategy to enhance DHA’s effectiveness against glioma." (PMID 39267831, 2024). "Consistent with the previous reports, RSL3, and erastin induced the time-dependent degradation of FTH1 and NCOA4 in glioma cells." (PMID 38886572, 2024). "Remarkably, both pharmacological (BafA1) and genetic (shAtg-5 and shAtg-7) inhibition of autophagy significantly diminished RSL3-induced FTH1 and NCOA4 degradation, indicating that autophagy mediates ferritin degradation in glioma cells during ferroptosis." (PMID 38886572, 2024). "Downregulation of matrix-remodeling-associated protein 8 (MXRA8) increases the intracellular levels of lipid peroxidation in glioma cells, leads to NCOA4 upregulation and inhibits ferritin heavy chain 1 (FTH1)." (PMID 36937406, 2023). "Surprisingly, we found FTH1, a negative regulator of ferroptosis, upregulated in DHA treated glioma cells." (PMID 36164395, 2022). "After construction of TUG1-overexpressed U87 and U251 glioma cells, as expected, the expression of MAZ and FTH1 at the protein level was significantly downregulated." (PMID 36164395, 2022). "Overexpression of TUG1 or inhibition of FTH1 expression enhances the antiglioma effect of DHA in vitro and in vivo, providing a promising method to enhance the antitumor effect of DHA in glioma." (PMID 36164395, 2022). "Thus, the COPZ1/NCOA4/FTH1 axis may be a novel therapeutic target in the treatment of gliomas." (PMID 33420375, 2021). "The LDA results revealed a significantly increased expression of iron metabolism-related genes ferritin heavy chain 1 (FTH1), transferrin receptor (TFRC), and Acyl-CoA synthetase long-chain family member 4 (ACSL4), while GPX4 expression was decreased in the glioma samples compared to the controls." (PMID 41154694, 2025). "Simultaneously, leveraging the mechanism by which FTH1 overexpression induces intracellular iron depletion to activate TfR upregulation, we will utilize the specific binding of TfR and Tf to deliver Tf-modified LPD (Tf-LPD) to glioma cells." (PMID 40723232, 2025). "Furthermore, consistent with glioma cells, double knockout Par-4−/− MEFs also significantly inhibited RSL3 or ML210-induced degradation of FTH1 and NCOA4." (PMID 38886572, 2024). "TUG1 overexpression or inhibition of FTH1 expression could enhance the antiglioma effect of DHA in vitro and in vivo, providing a promising strategy to enhance the antitumor effect of DHA in glioma." (PMID 36164395, 2022). "TCGA database investigations about the survival probability (SP) related to the PLIN1-5, FTH1, TFR1, and FPN gene expression in samples derived from patients suffering with bladder, breast, low-grade glioma, lung, and prostate cancers provided some evidences in accordance with our results." (PMID 34499029, 2021). "Consequently, orexin‐A may induce ferroptosis in gliomas by selectively targeting NFE2L2 and regulating the downstream expression of GPX4, TFRC and FTH1." (PMID 38685674, 2024).
hepatocellular carcinoma (31 papers, 2013 to 2026). A malignant tumor that arises from hepatocytes. "MELK regulated the AKT/mTOR signaling pathway, causing changes in the levels of GPX4, GSH, FTH1, xCT, heme oxygenase 1(HO-1), reactive oxygen species, and Fe2+ to regulate the ferroptosis of hepatoma cells." (PMID 37008632, 2023). "In myeloid leukemia, hepatocellular carcinoma, Hodgkin’s lymphoma, head and neck carcinoma, and pancreatic cancer, FTH1 has been shown to act as an oncogene." (PMID 40538534, 2025). "As an activator of TNFR, TNF-α elevated ferritin heavy chain 1 (FTH) expression via NF-κB signaling and inhibited apoptosis in serum-deprived hepatocellular carcinoma cells." (PMID 36944609, 2023). "It has been found that NRF2 can affect cell ferroptosis by regulating HO-1, GPX4, NQO1, and FTH1, which play important roles in the protection of hepatocellular carcinoma (HCC) cells from ferroptosis." (PMID 35899120, 2022). "A study revealed that NRF2 and FTH1 are both increased upon erastin treatment of hepatocellular carcinoma cells, suggesting that NRF2 stimulates FTH1 transcription upon ferroptosis." (PMID 33897873, 2021). "Specifically, NRF2-mediated induction of the iron-related target genes HMOX-1 and FTH1 protected against ferroptosis; consistently, knockdown of either HMOX-1 or FTH1 by RNA interference enhanced ferroptotic cell death in hepatocellular carcinoma cells." (PMID 28793787, 2018). "The circPIAS1/NUPR1 axis suppresses ferroptosis activity in hepatocellular carcinoma (HCC) cells by upregulating FTH1, thereby accelerating HCC progression." (PMID 40725394, 2025). "HO-1 also elicits anti-ferroptotic effects in hepatocellular carcinoma (HCC) cells since Nrf2 activation inhibits ferroptosis via p62-mediated Keap1 degradation, upregulating the actions of Nrf2 on its target genes, HO-1 and FTH1." (PMID 41470866, 2025). "Furthermore, FTH1 suppressed the ferroptosis of hepatocellular carcinoma cells and leukemia cells." (PMID 35635082, 2022). "Knockdown of FTH1 in hepatocellular carcinoma cells increased the incidence of ferroptosis, suggesting that FTH1 may play an important protective role in cellular ferroptosis and that reduced homeostasis in iron stores during the onset of ferroptosis may lead to iron overload." (PMID 34966478, 2021). "CREPT knockdown in hepatocellular carcinoma (HCC) leads to the diminished expression of NF-kB/NRF2 target genes, such as Sod2 and Fth1, contributing to the release of reactive oxygen species (ROS) accumulation and impaired liver function." (PMID 40723282, 2025). "The results of Western Blot showed that curcumin decreased the expression of ferroptosis-related proteins SLC7A11, GSS, GPX4, and FTH1, as well as increased the expression levels of PTGS2 and ACSL4 in hepatocellular carcinoma tissues." (PMID 39311951, 2024). "In hepatocellular carcinoma, the degradation of KEAP1 mediated by P62 assists the activation of NAD(P)H quinone dehydrogenase 1 (NQO1), heme oxygenase 1 (HO1), and ferritin heavy chain 1 (FTH1) down-stream of NRF2." (PMID 37152054, 2023). "FTH1,FTL is highly expressed in hepatocellular carcinoma cells and hepatocellular carcinoma tissues." (PMID 37555866, 2023). "ACO1, also known as IRP1, is an RNA-binding protein that controls iron homeostasis by regulating TFRC and FTH1 expression in CCA and hepatocellular carcinoma." (PMID 36733386, 2022). "In hepatocellular carcinoma, IGF2BP3 stabilizes NRF2 mRNA to inhibit ferroptosis; whereas in lung adenocarcinoma, it modulates multiple anti-ferroptotic regulators such as GPX4, SLC3A2, ACSL3, and FTH1 to confer ferroptosis resistance." (PMID 40530014, 2025). "In cancer research, the Nrf2 antioxidant signaling pathway has been shown to be involved in the protection of hepatocellular carcinoma cells from ferroptosis by regulating the expression of FTH1 but not TFR1." (PMID 39563478, 2024).
hepatocellular carcinoma (continued). "Furthermore, in hepatocellular carcinoma cells, knockdown of p62, NQO1, FTH1 and HMOX1 promoted ferroptosis in response to erastin and sorafenib." (PMID 34836129, 2021). "CircPIAS1 promotes hepatocellular carcinoma progression by inhibiting ferroptosis through the miR-455-3p/NUPR1/FTH1 axis, with NUPR1 inhibition sensitizing HCC cells to lenvatinib." (PMID 39315094, 2024).
iron deficiency (30 papers, 2013 to 2025). "Iron deficiency can impair muscle function and lead to anemia, further highlighting the importance of FTH1 in maintaining iron homeostasis in this tissue." (PMID 39941157, 2025). "When FTH1 expression is altered, it can lead to either iron deficiency or overload within the cells." (PMID 40507980, 2025). "This study developed an FTH1 expression system regulated by chimeric elements, leveraging the mechanism whereby FTH1 overexpression induces intracellular iron deficiency to activate upregulation of transferrin receptor (TfR) expression." (PMID 40723232, 2025). "Iron restriction in Ndufs4−/− mice downregulated FTH1 expression, consistent with iron deficiency anemia." (PMID 36799301, 2023). "Compared with other key roles in iron homeostasis (such as in activating CYBRD1), we found that TFRC, and IRP2 upregulation, and FTH1 downregulation were significantly induced after incubation with the miR-17-5p inhibitor in a degree of iron deficiency." (PMID 31423010, 2019). "We speculate that FTL may be more important for suppressing lipid peroxidation, while FTH1 primarily prevents anemia and preserves iron delivery to myelinating oligodendrocytes in the setting of functional iron deficiency." (PMID 39334701, 2024). "Glial activation by HIV may inhibit FTH1 release, reducing iron bioavailability and promoting functional iron deficiency in the brain, particularly in oligodendrocytes." (PMID 39334701, 2024). "Indeed, myeloid Fth1 deletion rescued intracellular iron deficiency in CKD kidney macrophages as it improved LIP and reduced TfR1." (PMID 36394951, 2023). "Interestingly we observed in this study that Jun and Kras appeared to directly up-regulate fth1, which acts as a buffer against iron deficiency and overloading." (PMID 23922661, 2013). "Thus, the data suggest that Fth1 delivered iron is responsive to CSF iron deficiency in females." (PMID 35689283, 2022). "In our proteomic study, the expression levels of FTL and FTH1 were both decreased in the high myopia group, while the TF abundance was increased in the high myopia group compared to the low myopia group, indicating the potential impact of iron deficiency on the progression of myopia." (PMID 34660571, 2021). "Intracellular iron deficiency activates IRP1, which increases the expression of iron uptake proteins TfR1 and DMT1 while decreasing levels of iron store protein FTH1 and sole iron export protein FPN1, ultimately leading to an increase in intracellular iron." (PMID 37755077, 2023). "Ferritin phagocytosis promotes erythropoiesis and the development of UTIs as follows: 1) During iron deficiency, NCOA4 selectively interacts with the FTH1 subunit of ferritin through its C-terminal domain and arginine residues on FTH1." (PMID 36160450, 2022). "The presence of iron-responsive elements (IREs) in FTH1 and FTL1 mRNAs, which can bind iron regulatory proteins (IRPs) under conditions of iron deficiency or oxidative stress, may contribute to translational repression." (PMID 40563331, 2025). "Iron deficiency or iron overload status prior to AOM/DSS treatment completely eliminated the elevated expression of FTH1 in the colon tissues of mice, regardless of iron status." (PMID 35631174, 2022). "In S. pombe, the mechanism of vacuolar iron mobilization in response to iron deficiency is not well understood and may differ due to the absence of orthologs for Smf3, Fre6, Fth1, and Fet5." (PMID 39980688, 2025). "Cells with lost miR-17-5p function showed a greater degree of iron deficiency, as evidenced by increased protein levels of IRP2, increased transferrin receptor (TFRC) mRNA expression, and decreased ferritin light chain (FTL) and ferritin heavy chain 1 (FTH1) mRNA expression." (PMID 31423010, 2019). "However, the expression level of FTH1 was maintained in cardiomyocyte-specific IREB1/2-deficient hearts with iron deficiency, suggesting that iron deficiency may not directly induce FTH1 degradation in cardiomyocytes." (PMID 33526170, 2021).
lung cancer (30 papers, 2020 to 2025). A malignant neoplasm involving the lung. "The principal intracellular iron‐storage protein, FTH1, is crucial for maintaining cellular iron homeostasis and is implicated in the prognosis of various types of cancer, including pancreatic cancer, lung cancer, liver cancer and others." (PMID 40038872, 2025). "Furthermore, the involvement of the lncRNA H19/miR-19b-3p/FTH1 axis in curcumenol's ferroptotic effects suggests a specific molecular mechanism underlying its impact on lung cancer cells." (PMID 39104501, 2024). "Based on these observations from the in silico study, we concluded the role of FTH1 as a tumor suppressor gene in lung cancer." (PMID 40538534, 2025). "Thereby, based on the publicly available data and previous reports, we have considered FTH1 a tumor suppressor in lung cancer, and our molecule is potent enough to induce its expression." (PMID 40538534, 2025). "Mechanistically, Huaier simultaneously and independently downregulates the antioxidant pathway SLC7A11/GPX4 and elevates intracellular iron levels through NCOA4-mediated ferritinophagy degradation of FTH1 in lung cancer cells." (PMID 40623982, 2025). "From the TCGA KM plotter, we have discovered that the low expression of the FTH1 level leads to poor survival in patients with lung carcinoma." (PMID 40538534, 2025). "To further investigate the role of FTH1 specifically in lung carcinoma, we used the TCGA km plotter and UALCAN database." (PMID 40538534, 2025). "Another example involved the indirect regulation of FTH1 by the natural drug curcumenol to trigger ferroptosis in lung cancer, thereby inhibiting the proliferation of lung cancer cells." (PMID 38742521, 2024). "Their research showed that ferroptosis was the mechanism by which curcumenol induced lung cancer cell death, and that the lncRNA H19/miR-19b-3p/FTH1 axis was crucial for this process." (PMID 38338400, 2024). "In radioresistant lung cancer cells, the expression of lipid Droplet (LD) and ferritin heavy chain (FTH1) increased and correlated with each other, which can be targeted and synergistically inhibit tumor radioresistance." (PMID 36865554, 2023). "The inhibition of miR-224-5p by circSnx12 and the inhibition of miR-19b-3p by lncH19 elevate FTH1 levels to repress curcumenol-induced ferroptosis in heart failure and lung cancer." (PMID 37686142, 2023). "In breast and lung cancer cells, silencing the FTH1 gene downregulated the amounts of LDs and induced radioresistance, and FTH1 overexpression as well as iron-chelating treatment by dseferoxamine were able to restore these effects." (PMID 36778122, 2023). "We found that co-treatment with MA and osimertinib in lung cancer cells significantly inhibited the expression of FTH1 compared with the osimertinib alone treatment group, which further activated the ferroptosis pathway and enhanced EGFR-TKI sensitivity." (PMID 36712673, 2022). "H19 acts as the “ceRNA” of miR-19b-3p and promotes the expression of FTH1, which plays a promoting role in lung cancer." (PMID 36188624, 2022). "In fact, breast and lung cancer cells silenced for the FTH1 gene showed a reduction in the LD numbers and, by consequence, became radiosensitive." (PMID 34499029, 2021). "Upon further investigation, we found that Huaier treatment resulted in a significant increase in NCOA4 protein levels and a decrease in FTH1 protein levels in the three distinct lung cancer cell lines consistently, but did not alter the transcription level of these genes in these cell lines." (PMID 40623982, 2025). "This lncRNA H19/miR-19b-3p/FTH1 axis is crucial for mediating curcumenol-induced ferroptotic cell death, highlighting the role of ncRNAs in modulating the effects of natural compounds on ferroptosis in lung cancer." (PMID 39104501, 2024).
lung cancer (continued). "MiR-335, miR-224-5p, and miR-19b-3p directly reduce FTH1 expression by binding to its mRNA, leading to an increase in free iron and the promotion of ferroptosis in Parkinson’s disease, heart failure, and lung cancer." (PMID 37686142, 2023). "Furthermore, MA induces ferroptosis by suppressing the NRF2-SLC7A11 axis and mitochondrial Ca2+ overload induced-FTH1 pathways to promote the sensitivity of osimertinib-resistant lung cancer cells to osimertinib." (PMID 36712673, 2022). "In conclusion, our study shows that MA is a novel EGFR-TKI sensitizer in KRAS-mutated and osimertinib-resistant lung cancer cells by suppressing the KRAS-ERK pathway and inducing ferroptosis via suppressing NRF2-SLC7A11 axis and mitochondrial Ca2+ overload induced-FTH1 pathways." (PMID 36712673, 2022). "However, mRNA levels of NRF2 and its target genes HO-1, GCLC, and FTH1 were significantly increased in the A549 or H460 lung cancer cell lines stably transfected with these five KEAP1 mutants." (PMID 32576270, 2020). "In another study on the mechanism of lung cancer, it was found that lncRNA H19 may inhibit the transcription level of FTH1 by competitively binding miRNA-19b-3p, so as to protect lung cancer cells from iron death injury, thus weakening the effect of anticancer drugs." (PMID 35844870, 2022). "Correlation analysis using the cancer tool suggests that FTH1 has a positive correlation with MAP1LC3B and pro-apoptotic protein BAX, whereas it is negatively correlated with the anti-apoptotic protein Bcl2 in lung carcinoma." (PMID 40538534, 2025). "MiR-19b-3p directly targets and reduces ferritin heavy chain 1 (FTH1) expression, resulting in increased free iron and promoting ferroptosis in lung cancer." (PMID 39763590, 2024). "Both Curcumenol and Ginsenoside Rb3 inhibit H19 expression through the H19/miR-19b-3p/FTH1 axis and the H19/miR-29b-3p/HGMB1/TLR4 axis to promote ferroptosis in lung cancer cells and reduce inflammation." (PMID 36188624, 2022). "Compared with A549 or H460 lung cancer cell lines stably transfected with empty vector, mRNA levels of NRF2 and its target genes HO-1, GCLC, and FTH1 were significantly decreased after the cell lines were stably transfected with WT KEAP1." (PMID 32576270, 2020). "Similarly, the previously discussed manoalide (MA) that can induce ferroptosis of lung cancer through NRF2-SLC7A11 and FTH1 pathways, can also affect mitochondrial Ca2+ overload." (PMID 39104501, 2024). "lncRNA H19 can act as a competitive endogenous RNA to bind to miR-19b-3p, thereby enhancing the transcriptional activity of its endogenous target ferritin heavy chain 1(FTH1), and CUL plays a role in promoting ferroptosis by down-regulating lncRNA H19 in lung cancer cells." (PMID 37005430, 2023). "In tackling resistance to EGFR-TKI in lung cancer, Manoalide has been shown to effectively enhance the sensitivity of lung cancer cells to osimertinib by inhibiting the NRF2-SLC7A11 axis and inducing ferroptosis by down-regulation of ferritin heavy chain 1 through mitochondrial Ca2+ overload." (PMID 38515565, 2024). "Finally, the effect of EC on ferroptosis in lung cancer cells was tested, and the results revealed that EC treatment significantly increased the Fe2+ concentrations in H460 and H1299 cells while inhibiting the expression of the ferroptosis-related proteins SLC7A11, GPX4, and FTH1." (PMID 39480832, 2024).